MMP13 (matrix metallopeptidase 13)
Diseases named in the same sentence as MMP13 in open-access papers (continued):
Sharing a sentence is not in itself a finding about the gene and the disease.
tumor (continued). "From this, they were able to induce matrix MMP3 and MMP13 expression specifically upon ligation of the CAR and its antigen to remodel tumor microenvironment, increase T cell infiltration, and reduce tumor growth in vivo." (PMID 33790906, 2021). "MMP13 is a metalloproteinase whose higher activity is typical in BC and its abnormal activity was initially identified in TNBC tumours." (PMID 33807045, 2021). "We found that in all tumor cell lines, the level of VEGF and MMP13 in culture medium was significantly higher after treatment with VX765 compared to Nigericin and LPS/Nigericin and untreated controls (p < 0.05)." (PMID 33613529, 2020). "Western blot results revealed that the levels of p‐STAT3 (Tyr705), vimentin, MMP‐13, and MMP‐3 decreased in the tumor tissues grown from HeLa cells in the RES pretreatment and treatment groups, compared with those in the respective control groups." (PMID 33040485, 2020). "Based on the results of sequencing and bioinformatics analysis, MMP13 and COL1A1 were reported to contribute to the occurrence and development of tumor, especially the metastasis of tumor." (PMID 33014334, 2020). "The protein levels of vimentin, MMP‐13, and MMP‐3 markedly decreased in the tumor tissues grown from HeLa cells in the RES pretreatment and treatment mouse models compared to those in their respective control groups." (PMID 33040485, 2020). "The expression pattern of matrix metalloproteinase 13 (MMP13) is directly proportional to the SNHG12 expression, and the degradation of MMP13 in TNBC promotes tumor metastasis and invasion." (PMID 32575858, 2020). "Some studies suggest that RUNX2 has the ability to transactivate its downstream target genes, such as MMP9, MMP13, VEGF, survivin, and IL-8, which are involved in tumor progression, invasion, and metastasis." (PMID 33313404, 2020). "Nonetheless, we cannot exclude additional, direct effects of MMP13 and the other Notch targets on tumor cells, as we showed positive immunoreactivity for HES1, DLL4, and MMP13 proteins in iCCA cells." (PMID 32042099, 2020). "U. dioica extract treatment decreased miR-21 expression, which substantially reduced the overexpressed MMP1, MMP9, MMP13, vimentin and CXCR4, and increased E-cadherin in the treated tumor cell lines." (PMID 31362429, 2019). "The ability of RUNX2 to enhance the metastatic potential of tumor cells is largely based on its ability to regulate genes crucial to tumor progression including VEGF, MMP9, MMP13, OPN, SNAI 1–2, TWIST1 and TIMP13." (PMID 31395086, 2019). "Periostin is a driver of the EMT and induces expression of MMP-9, MMP-10, and MMP-13, resulting in the degradation of ECM, believed to be crucial for local tumor spread and/or metastasis via invasion and neovascularization." (PMID 29758011, 2018). "Taken together, MMP-13 over-expression was triggered by hypoxia/HIF-1α as an important mechanism to induced EMT and tumor invasion in NPC." (PMID 29515112, 2018). "It is therefore possible, that reduction in MMP13 and MMP1 production after AIM2 knockdown impairs implantation of cSCC cells in the skin of SCID mice and this way results in delay in tumor growth." (PMID 28526809, 2017). "Here, we show that pharmacological inhibition of LSD1 inhibits the aggressive features of OSCC by inhibiting key target genes that function in the tumor microenvironment and EMT, including CCN2/CTGF, MMP13, LOXL4 and vimentin." (PMID 29088714, 2017). "To investigate the relationship between MMP‐13 and MMP‐2 expression and tumour blood supply patterns in different stages of LCLC, we examined the expression levels of MMP‐13 and MMP‐2 and tumour blood supply patterns in different stages of LCLC." (PMID 28766880, 2017). "MMP-13 becomes secreted to the extracellular environment, where it degrades the extracellular matrix (ECM) to promote tumor invasion." (PMID 28127051, 2017).
tumor (continued). "GSK-LSD1 inhibited tonsillar SCC patient-derived tumor xenografts and inhibited CCN2/CTGF, MMP13, LOXL4 and vimentin expression whereas the expression of the tumor suppressor E-cadherin increased." (PMID 29088714, 2017). "Our data also demonstrates significant up-regulation of COL11A1, COL10A1, MMP1 and MMP13, and significant down-regulation of COL6A6 and DLK1 in tumor relative to non-tumor adjacent breast tissue." (PMID 27857161, 2016). "MMP14 can cleave a variety of substrates, including cell surface proteins (such as CD44) and other MMPs (such as pro-MMP2 and pro-MMP13), and induce ECM degradation and tumor cell invasion by increasing the secretion of other MMPs." (PMID 27564100, 2016). "The level of MMP-13 is up-regulated by a multifunctional growth factor called TGF-β, which exerts various effects on ECM deposition, tumor cell proliferation and progression." (PMID 27271600, 2016). "COL11A1, COL10A1, MMP1 and MMP13 are highly expressed in aggressive molecular subtypes (basal and HER2 tumors) in the Lebanese as their expression increases tumor migration and proliferation." (PMID 27857161, 2016). "MMPs were reported to induce tumor progression in HCC including MMP-1, MMP-2, MMP-3, MMP-7, MMP-9, MMP-11 and MMP-13." (PMID 26882566, 2016). "Our current study showed MALAT-1 knockdown modulated the expression of MMP13 and MMP19, members of the matrix metalloproteinase (MMP) family of proteins that are involved in altered extracellular matrix metabolism, tumor progression and metastasis." (PMID 27227769, 2016). "Thus, MMP-13 could be a useful indicator for tumor behavior and prognosis of CRC." (PMID 27716617, 2016). "There was also a significant increase in the expression of MMP13 (P = 0.0169), S100P (P = 0.0234) and COL10A1 (P = 0.024) compared with expression in the corresponding non-tumor tissue." (PMID 27857161, 2016). "Inflammatory cells surrounding BCC are typically positive for MMP-13, MMP-1, and MMP-9, indicating an essential role of inflammation in modulating tumor progression." (PMID 27271600, 2016). "Previous studies have shown that S100A4 expression can upregulate the matrix metalloproteinases (MMPs), which play critical role in tumor metastasis through degradation of extracellular matrix (ECM), including MMP-9, MMP-13, and MMP-2." (PMID 26903691, 2016). "Of note, tumor-induced MDSC are enriched for multiple ecto-proteases including ADAM28, ADAM9, collagenase-3 (MMP13), stromelysin (MMP3), macrophage elastase, and leukocyte elastase." (PMID 27929373, 2016). "In order to take a step into the mechanism of BCYRN1’s regulating tumor cell metastasis, the RNA and protein levels of representative MMPs, namely MMP9 and MMP13, were respectively measured." (PMID 25866480, 2015). "We thus speculate that MMP-13 may inhibit VM formation by degrading Ln-5γ2′ and Ln-5 γ2x into smaller cleavage fragments that interfere with the molecular signal transition required by the vasculogenic phenotype of tumor cells and ultimately prevent the formation of VM patterns." (PMID 25749207, 2015). "Another specific MMP, collagenase-3 (MMP-13), has broad substrate specificity and potentially affects tumor metastasis and invasion." (PMID 25749207, 2015). "Among these differentially expressed genes, MMP1, MMP12, MMP13 and MMP28 were consistently reduced in hnRNP K-knockdown cells but elevated in tumor cells." (PMID 24885469, 2014). "Our results that MMP-7 and MMP-13 were absent from areas of diffuse invasion and high malignancy, in good correlation with Bryne's malignancy grading of tumour structure and nuclear polymorphism, suggest that together these two MMPs might be useful as predictive markers of invasiveness in OSCC." (PMID 26019601, 2014). "We have recently reported that MMP-13 was identified as a common up-regulated gene by HNSCC invasion-related factors and involved in tumor angiogenesis." (PMID 24531055, 2014).
tumor (continued). "In this study, the correlation between angiogenesis and the expression of MMP13 and TGF-β1 also confirmed that the tumor microenvironment was crucial to the promotion of tumor recurrence and metastasis." (PMID 24581230, 2014). "Also at the tumor periphery, Collagen I protein levels were significantly increased in MMP13 KO versus wildtype animals as quantified by immunofluorescence staining, suggesting that depletion of this collagen degrading enzyme from host cells increases tumor Collagen I content." (PMID 24010522, 2013). "The 5 randomly selected gene expression changes observed using the Human Tumor Metastasis RT2 Profiler PCR array (CXCR4, CXCL12, MMP2, MMP9 and MMP13) were confirmed using qPCR." (PMID 24179538, 2013). "In response to collagen synthesis, we observed increased expression of matrix metalloproteinases (MMPs), such as MMP-13 and MMP-9, the latter facilitates the tumor cells to invade the extracellular matrix." (PMID 22690114, 2012). "MMP-13 expression has previously been evaluated only in human tumors, for which MMP-13 involvement in tumor invasiveness was unclear." (PMID 21726449, 2011). "Our data suggest that lymph node status, tumor size, Her-2/neu expression, TIMP-1 and MMP-13 expression in cancer cells are independent prognostic factors." (PMID 18373849, 2008). "MMP-13 also correlated with the expression of Her-2/neu (p = 0.015) and TIMP-1 (p < 0.010), respectively in tumor cells." (PMID 18373849, 2008). "Thus, nuclear MMP-13 staining may help to identify a category with worse prognosis in this tumor." (PMID 18554405, 2008). "MMP13, a member of the matrix metalloproteinase (MMP) family, is involved in the degradation of various extracellular matrix components and is crucial to tissue remodeling, inflammatory responses, and tumor progression." (PMID 40909948, 2025). "Tumor xenograft model mice were conducted, and in vivo assays further confirmed that miR-MTCO3P38 restrained tumor growth and proliferation in HCC by inhibiting the TMOD1/MMP13 pathway." (PMID 39744479, 2025). "Afterwards, in vitro and in vivo experiments showed that overexpression of TMOD1 reversed the inhibitory effects of miR-MTCO3P38 on migration and invasion of HCC cells and tumor growth, illustrating that miR-MTCO3P38 restrained tumor growth and development by targeting TMOD1/MMP13 pathway." (PMID 39744479, 2025). "In vivo, tumor growth was measured, and the impacts of miR-MTCO3P38 and its target gene on tumor pathology, proliferation, TMOD1/MMP13 pathway and tumor invasion-related factors were evaluated by hematoxylin-eosin staining, immunohistochemistry (Ki67) and western blot." (PMID 39744479, 2025). "As MMP13 can activate MMP9 by cleaving the inactive pro-MMP9 forms, its action on MMP9 activation facilitates tumour cell intravasation into vascular and lymphatic systems at primary tumour sites." (PMID 40243781, 2025). "The results showed that inhibiting or conditionally knocking out MMP-13 significantly enhanced immune reinstatement and improved immunotherapy efficacy, emphasizing that tumor-induced comprehensive effects from OP-GMP crosstalk persist beyond tumor presence." (PMID 40103824, 2025). "After that, we analyzed the protein expression levels of CDH5, MMP9 and MAPK1 in normal kidney tissues and ccRCC by CPTAC database, MMP13 for included in CPTAC database, and the protein expression levels of CDH5, MMP9 and MAPK1 were significantly higher than that in normal tissues in tumor tissues." (PMID 38580922, 2024). "Analysis of the DEGs in TCGA tumours revealed that the miR-18a/low tumours expressed high levels of EMT master regulators-ZEB1 and ZEB2 and Matrix metalloproteinases, MMP2, MMP3, MMP10, MMP11, MMP13 and MMP17 (p < 0.05)." (PMID 38786043, 2024).
tumor (continued). "MMP-13 promotes tumour angiogenesis 16, MMP-7 degrades HB-EGF and E-cadherin in the basement membrane 17, 18, and MMP-14 degrades CD-44 and electron-cadherin in the basement membrane 19, which together play a vital role in tumour invasion." (PMID 38911387, 2024). "The positive rate of serum EFNA1 + MMP13 was not significantly correlated with clinical data such as age, gender, depth of tumor invasion, lymph node status, TNM stage, early-stage or late-stage GC (all P > 0.05)." (PMID 38987376, 2024). "Cluster C0, for instance, expressed high levels of matrix metalloproteinases (MMP13, MMP11) and alpha‐smooth muscle actin (ACTA2), a well‐known myofibroblast marker, signifying the presence of myofibroblasts known to promote tumour progression and angiogenesis." (PMID 38445456, 2024). "A small number of MMP13+ cells were localized to the front lines where infiltrating immune cells attacked tumor cells, but neither MMP3+ nor MMP9+ cells were localized." (PMID 38774209, 2024). "PyMT-driven mammary carcinogenesis has been shown to upregulate MMP-13 with no promotion of tumour growth." (PMID 37297024, 2023). "Distinct from its role in tumor progression and tissue remodeling, MMP-13 proteolytic activity is not required for a series of inductive effects, including promoting OCL multinucleation and bone resorption." (PMID 37460553, 2023). "ATF3 is also known as an activator of the tumor invasive potential by up-regulating the expression of the matrix metalloproteinase (MMP) family members (i.e., MMP-1, MMP2, MMP-9 and MMP-13), whose mRNA and protein abundance are correlated with BC invasion and metastasis." (PMID 37447165, 2023). "MMP-13 expression is regulated by Serpine1 (PAI-1), which is known to inhibit the plasminogen activator enzyme and is related to malignancies by influencing tumor invasion, angiogenesis and metastasis." (PMID 37994159, 2023). "Furthermore, CAFs secrete MMP-1, MMP-3, MMP-7, MMP-9, and MMP-13, releasing ECM-bound growth factors such as VEGF supporting tumor angiogenesis." (PMID 35572966, 2022). "MMP-13 expression was also found to be not just in tumor cells but also in the cells that surround epithelial tumor cells (called stromal cells)." (PMID 36505148, 2022). "Tumour hypoxia can also trigger the expression of hypoxia-inducible transcription factor (HIF)-1, which directly promotes MMP-13 gene expression by binding to the MMP-13 promotor or indirectly through promotion of the expression of the growth factors or cytokines that regulate MMP-13 expression." (PMID 35805035, 2022). "Furthermore, the knockdown of MMP-13 at the tumor-bone interface by treatment with MMP-13 antisense oligonucleotide significantly reduced bone destruction, indicating that MMP-13 contributes to breast cancer-induced osteolysis." (PMID 36741729, 2022). "Increased MMP-13 expression correlated with tumor type (diffuse gastric cancer) and tumor stage in the intestinal gastric carcinomas, but not with H. pylori infection." (PMID 35163805, 2022). "Of note, MMP13 was specifically expressed within the tumor and not in the normal component; ST6GAL2 and ENPP1 were highly expressed in tumor tissue compared to adjacent normal tissue (log2-foldchange 4.26 and 2.94, respectively)." (PMID 35365682, 2022). "Indeed, tumor cells attenuate the immune anti-tumoral action by MMP-2, MMP-9, MMP-13, and MMP-14 secretion, leading to T-cell activity hindrance." (PMID 35572966, 2022). "In addition, increased expression of several genes in the TME known to drive expression of HCC tumor-derived TIMP1 and MMP13 was observed." (PMID 33995488, 2021). "Moreover, we have investigated the stromal score, immune score, and tumor purity of five subtypes, along with the estimate score of MMP1, MMP2, MMP9, MMP12, MMP13 in five subtypes of BRCA." (PMID 35069702, 2021).
tumor (continued). "MMP2 (log2 fold change = 7.47), MMP9 (log2 fold change = 3.63), and TIMP2 (log2 fold change = 2.66) displayed increased expression in the TME, while MMP13 (log2 fold change = −4.41) and TIMP1 (log2 fold change = −2.26) displayed increased expression in the HCC tumor." (PMID 33995488, 2021). "In this study, overexpression of MMP13 and TIMP1 was observed in the HCC tumor cells." (PMID 33995488, 2021). "MMP13, one of the MMPs, is capable of cleaving various components of the ECM, and adhesion proteins are found to be significantly upregulated in NAFLD and contribute to tumor cell extravasation and establishment of metastases in the liver microenvironment." (PMID 32742469, 2020). "The expression levels of MMP7 (P = 0.0123) and MMP13 (P = 0.0147) were significantly increased in the metastatic tumour samples, while that of MMP10 (P = 0.0932) was not." (PMID 31996191, 2020). "Thus, we have demonstrated that the crucial contribution of MMP13 on tumor progression allows the maintenance of angiogenesis, which is indirectly blocked by LY3039478 through the inhibition of MMP13." (PMID 32042099, 2020). "Hence we validated gene expression of MMP1, MMP3, MMP11, MMP13, MMP14, ADAMTS1 and ADAMTS5 genes belonging to metallopeptidase activity, using qPCR in 67 tumours." (PMID 31292488, 2019). "Furthermore, ING2 can ablate the expression of the candidate proto-oncogene CIP2A, whereas transcription of matrix metalloproteinase 13 (MMP13) can be activated or repressed by ING2, depending on the cancer type analyzed, thereby regulating tumor invasiveness." (PMID 31752342, 2019). "Furthermore, we demonstrated that MMP13 inhibition disturbs proliferation, migration, and invasion induced by ETV4 and participates to ETV4-induced tumor formation in immunodeficient mice." (PMID 29996935, 2018). "Furthermore, systemic treatment of SIS3 also significantly altered the tumour-friendly microenvironment, including suppression on angiogenesis (VEGF expression and CD31+ vessels) and tumour-invasive factors (MMP-2, MMP-9, MMP-13 and CXCR4)." (PMID 28262747, 2017). "In addition, the suppressive effect of SIS3 on cancer progression was also associated with inhibition of angiogenesis (CD31 and VEGF) and tumour-invasive and metastatic activities, including the expression of MMP-2, MMP-9, MMP-13 and CXCR4." (PMID 28262747, 2017). "MMP-13 also promotes the secretion of VEGF-A from fibroblasts and endothelial cells, and it is suggested that MMP-13 may directly and indirectly promote tumor invasion and angiogenesis both in vitro and in vivo." (PMID 28068383, 2017). "With tumour growth, certain factors, such as persistent tumour hypoxia‐mediated activation of HIF‐2α 29, may promote transcription and high expression levels of MMP‐13 30, which plays a role in inhibiting the formation of VM through Ln‐5 degradation." (PMID 28766880, 2017). "In addition to MMP-13, other MMPs, such as MMP-2 and membrane type 1-MMP (MT1-MMP), also promote tumor invasiveness." (PMID 28127051, 2017). "Furthermore, Mmp2, Mmp9, and Mmp13 become upregulated in MMTV-PyMT tumors and are also involved in tumor growth and metastasis." (PMID 27542270, 2016). "The expression of MMP-13 is not confined to tumor cells alone, as its expression is up-regulated in stromal cells surrounding epithelial tumors including fibroblasts, inflammatory cells, and endothelial cells." (PMID 27271600, 2016). "MMP-8 and MMP-13 are classified as collagenases because they mainly degrade collagen; MMP-13 is able to degrade the components of the basal membrane and is involved in tumor dissemination and progression." (PMID 27782083, 2016). "A high MMP-13 staining index was significantly more frequent in tumor cells from invasive lesions (24/27) as compared to non-invasive lesions (0/4) (p = 0.001, Fisher’s exact test)." (PMID 26193700, 2015).